LINC02283 (long independently transcribed non-coding RNA 2283)
Gene: Long non-coding RNA gene on chromosome 4 (54,332,727 to 54,376,753, forward strand). Ensembl gene ENSG00000248184.
Diseases named in the same sentence as LINC02283 in open-access papers:
LINC02283 is named in the same sentence as 2 diseases in open-access papers, as found by Europe PMC text mining. Sharing a sentence is not in itself a finding about the gene and the disease.
LINC02283 shares sentences with these, for which no sentence is quoted: astrocytoma (1 paper); glioma (1).